ABI3BP (ABI family member 3 binding protein)
Diseases named in the same sentence as ABI3BP in open-access papers (continued):
Sharing a sentence is not in itself a finding about the gene and the disease.
cancer (continued). "Since EMT plays a crucial role in cancer metastasis, we examined whether ABI3BP influences EMT markers in NSCLC cells." (PMID 40092729, 2025). "The ABI3BP expression was significantly correlated with the abundance of infiltrating immune cells: B cells in seven cancers, NK cells in seven cancers, Mast cells in six cancers, Macrophage M2 cells in six cancers, and T cell CD4+ memory resting in six cancers." (PMID 37197424, 2023). "We also examined ABI3BP expression at various cancer stages." (PMID 37197424, 2023). "Consequently, we analyzed the expression of mRNA and protein of ABI3BP in pan-carcinoma using public databases and immunohistochemistry." (PMID 37197424, 2023). "We first investigated the expression of ABI3BP in pan-carcinoma and immune-related activities." (PMID 37197424, 2023). "The forest plot shows the univariate cox regression results of ABI3BP to OS in TCGA pan-carcinoma." (PMID 37197424, 2023). "Its application in five cancers (colon, liver, kidney, stomach, or thyroid; total samples n = 2024) identified various dysregulated key features (such as PVT1 expression and ABI3BP alternative splicing) and pathways (especially liver and kidney dysfunction) shared by multiple cancers." (PMID 34946814, 2021). "Studies have attested the anti-oncogenic role of ABI3BP indicating that the ectopic expression of ABI3BP could weaken cancer cell growth properties and induce senescence." (PMID 31174563, 2019). "We have previously shown that ABI3BP expression is lost in most malignant carcinomas." (PMID 21223585, 2011). "ABI3BP’s activity is not limited to lung cancer; it has also demonstrated tumor-suppressive functions in other malignancies, such as esophageal and breast cancers, where it downregulates oncogenic signals, making it a versatile tumor suppressor across different cancer types." (PMID 40092729, 2025). "Our findings indicate that abnormal ABI3BP expression may serve as a cancer biomarker." (PMID 37197424, 2023). "However, the relevance of ABI3BP in different forms of cancer is uncertain." (PMID 37197424, 2023). "ABI3BP is a potential partner of ABI3, and previous studies have shown that their expression levels are synchronized during cancer progression." (PMID 37942289, 2023). "In addition, abnormal expression of ABI family, member 3 binding protein (ABI3BP); klotho beta (KLB); long non-coding RNA metastasis-associated lung adenocarcinoma transcript 1 (MALAT1); and particular microRNAs, including miR-1206 and miR-612, has been observed in cancer cells." (PMID 26039424, 2015). "We not only observed that ABI3 expression is reduced or lost in most carcinomas but also that there is a positive correlation between ABI3 and ABI3BP expression." (PMID 21223585, 2011). "An interesting observation in multi-transcript genes is worth noting; first, the highest number of transcripts per gene that correlated with a phenotype in a cancer type was 19, and was limited to the CD36 (19 out of 24 transcripts), ABI3BP (19/29), and TCF4 (19/93) genes." (PMID 41048343, 2025). "ABI3BP expression was interpreted using the Cancer Genome Atlas (TCGA) database, the Genotype Tissue Expression Atlas (GTEx) database, the Human Protein Atlas (HPA) database, the Cancer Cell Line Encyclopedia (CCLE) database, and immunohistochemistry." (PMID 37197424, 2023). "Moreover, there is existing literature demonstrating the important roles of ABI3BP, WASF2, RUNX1T1, and TNFAIP8L2 in cancer processes through pan-cancer analysis." (PMID 37942289, 2023). "However, both ABI3BP and ABI3 are downregulated in cancers with supporting evidence that they are both important in promoting cellular senescence." (PMID 30923710, 2019). "However, there are no studies on the effect of ABI3BP on immune infiltration and prognosis in pan-cancer." (PMID 37197424, 2023).
tumor (19 papers, 2015 to 2025). "Reduced expression of ABI3BP has been associated with tumor progression and metastasis, highlighting its pivotal role in tumor suppression." (PMID 40092729, 2025). "ABI3BP, a recently discovered extracellular matrix protein, has been linked to tumor development in numerous studies." (PMID 38812032, 2024). "In conclusion, the association between ABI3BP and patient prognosis, clinical data, gene alterations, and tumor immune infiltration provides novel information for future clinical diagnosis and therapy." (PMID 37197424, 2023). "Immune infiltration of tumor cells is tightly associated with ABI3BP expression." (PMID 37197424, 2023). "B cell, CD8+ T cell, T cell follicular helpers, Th1 cells, Th2 cells, Th17 cells, Treg cells, T cell exhaustion, Macrophages M1, Macrophages M2, Tumor-Associated Macrophages, Monocytes, Natural Killer cells, Neutrophils, and Dendritic cells express ABI3BP to varying degrees." (PMID 36744181, 2022). "Further, we hypothesize that mutations in ABI3BP and related genes may act through tumor immune infiltration." (PMID 36744181, 2022). "Collectively, ABI3BP functions as a tumor suppressor in NSCLC by targeting the MAPK/ERK axis, thereby regulating cell proliferation, motility, and EMT." (PMID 40092729, 2025). "In summary, our study highlights the tumor-suppressive role of ABI3BP in NSCLC, revealing its ability to regulate key signaling pathways involved in cell proliferation, migration, and EMT." (PMID 40092729, 2025). "In contrast, ABI3BP was markedly under expressed, consistent with prior reports suggesting a tumor-suppressive role." (PMID 41228302, 2025). "The re-expression of ABI3BP in nude mice tumor model results in the inhibition of cell growth, activity, migration, and overall tumor growth." (PMID 38812032, 2024). "Knocking down ABI3BP expression has been shown to inhibit tumor growth by affecting tumor cell proliferation, viability, migration, and invasion." (PMID 38812032, 2024). "ABI3BP expression was negatively correlated with age in most tumor tumors, including GBMLGG, LGG, TGCT, STAD, KIRC, and BRCA." (PMID 37197424, 2023). "In 10 malignancies, we found a strong correlation between ABI3BP expression levels and tumor stages." (PMID 37197424, 2023). "ABI3BP expression was also linked to immune checkpoint genes, TMB, MSI, and other tumor heterogeneity factors." (PMID 37197424, 2023). "ABI3BP was associated with an increase in B cell, T cell CD4+, T cell CD8+, Macrophage, and Neutrophil infiltration of tumor cells, as determined by additional analyses of immune infiltration." (PMID 37197424, 2023). "And ABI3BP was associated with a significant Immune score the top three for COAD, COADREAD and LUSC tumor." (PMID 37197424, 2023). "ABI3BP mRNA expression was shown by differential analysis to be down-regulated in 16 tumor types relative to normal tissues, corresponding with its protein expression level as determined by immunohistochemistry." (PMID 37197424, 2023). "Meanwhile, aberrant expression of ABI3BP was associated with immune checkpoints, TMB, MSI, tumor purity, HRD, LOH, and drug sensitivity." (PMID 37197424, 2023). "The results indicated that the expression level of ABI3BP in tumor tissues was significantly lower than that of normal tissues, and it was higher in a small percentage of tumors." (PMID 37197424, 2023). "The CCLE database displays ABI3BP expression levels in 32 tumor cell lines, with the MESO cell line expressing the highest levels and the CLL cell line displaying the lowest levels." (PMID 37197424, 2023).
tumor (continued). "To further our understanding of the relationship between ABI3BP and immune invasion, we used the TISIDB library to evaluate the relation of expression of ABI3BP and numerous immunity signals, including 28 tumor immunity Lymphocyte sub-types." (PMID 36744181, 2022). "ABI3BP acts as a gene that suppresses tumor growth during the growth and metastasis of gallbladder carcinoma at the cellular level." (PMID 36744181, 2022). "Next, we used the “immunedeconv” package to demonstrate the relationship between ABI3BP and tumor immune cells in LUAD and LUSC, respectively." (PMID 36744181, 2022). "In conclusion, ABI3BP contributes significantly to the regulation of numerous immunity molecules in lung tumors, hence influencing the immunoinfiltration in tumor micro-environments." (PMID 36744181, 2022). "In AK versus normal skin, five SMGs were significantly downregulated in at least two datasets (KIF24, KCNK5, EPB41L, INSIG2, and ABI3BP), suggesting a tumor suppressor role." (PMID 33482222, 2021). "Interrogating published expression datasets against our SMG list found KIF24, KCNK5, EPB41L2, and ABI3BP downregulated in AK compared with those in the normal skin, suggesting tumor suppressor roles." (PMID 33482222, 2021). "Human ABI3BP was originally identified as a novel NESH-binding protein that is involved in tumor cell migration and mobility." (PMID 32774142, 2020). "We showed for the first time that ABI3BP is downregulated in EC, revealing the role of ABI3BP as a tumor suppressor gene in the progression of EC growth and metastasis at the cellular level." (PMID 32774142, 2020). "In our future work, the mechanism of ABI3BP involved in its tumor-suppressive effects will be studied in detail, and ABI3BP will be explored as an effective target for tumor diagnosis and as a biomarker." (PMID 32774142, 2020). "The results obtained revealed that the tumor size in the mice treated with over-expressed ABI3BP was smaller than that in the vector-NC group (p < 0.05)." (PMID 31174563, 2019). "Immunohistochemistry were subsequently was used to detect the expression of ABI3BP in tumor tissues of each group." (PMID 31174563, 2019). "The roles of MALAT1, EZH2 and ABI3BP in the development of GBC were further explored through xenograft tumor in nude mice." (PMID 31174563, 2019). "Notably, ABI3BP interacts with oncogenic pathways, potentially serving as a multifaceted regulator of tumor biology." (PMID 40092729, 2025). "ABI3BP was related with tumor-infiltrating lymphocytes in LUAD and LUSC, respectively." (PMID 36744181, 2022). "TCGA was then utilized to evaluate expression of ABI3BP in tumor samples and regular tissues." (PMID 36744181, 2022). "This suggests that increased expression of ABI3BP in tumors may interfere with the tumor immune microenvironment by affecting immune cell infiltration, thereby affecting tumor progression." (PMID 36744181, 2022). "ABI3BP was considered to have a tumor-suppressive effect in thyroid cancer." (PMID 32774142, 2020). "Through its interaction with NESH, ABI3BP may exert a great effect on the progression of tumor cells." (PMID 32774142, 2020). "The flow cytometry assay revealed that ABI3BP could obviously increase the rate of apoptosis, while miR-183 could significantly reduce the rate of apoptosis, which suggested that ABI3BP plays a role as a tumor suppressor and that miR-183 is an oncogene." (PMID 32774142, 2020). "ABI3BP has been suggested to have tumor suppressive abilities in thyroid carcinoma." (PMID 31174563, 2019). "ABI3BP plays an important role in the proliferation of replicative senescence and may serve as a trigger of tumor development." (PMID 29301256, 2018). "Our research indicates that ABI3BP may be an essential immune target during tumor development." (PMID 37197424, 2023). "After further discussion, ABI3BP may become a new tumor marker." (PMID 36744181, 2022).
tumor (continued). "ABI3BP, which is reexpressed in the thyroid cells, has been reported to trigger cellular senescence through affecting the p21 pathway, resulting in a reduction in transformation activity, cell growth, viability, migration, invasion, and tumor growth in nude mice." (PMID 36193505, 2022). "In this study, we observed that overexpression of ABI3BP in NSCLC cells led to reduced proliferation and invasion, consistent with its known role as a tumor suppressor." (PMID 40092729, 2025). "ABI3BP’s interactions with key signaling pathways, including MAPK/ERK and PI3K/Akt, are essential for its tumor-suppressive activities." (PMID 40092729, 2025). "In terms of upregulated DEGs, seven genes (ABI3BP, CTSG, DPP4, CCL18, OSR2, GRIA3, MMP2) demonstrated reduced expression in tumor compared to normal tissue." (PMID 39062832, 2024). "We found a significant correlation between ABI3BP and tumor purity in BRCA, STAD, and STES after a comprehensive examination of the relationship between abnormal gene expression of ABI3BP and tumor purity." (PMID 37197424, 2023). "ABI gene family member 3-binding protein (ABI3BP) is involved in the regulation of actin cytoskeleton reorganization and cell movement and has been reported to act as a tumor suppressor." (PMID 37444464, 2023). "Staining for CADM3, IGLON5, and TGFB1 was low in tumor tissue; staining for LEP and ABI3BP was medium in tumor tissue; staining for CD1B was high in tumor tissue." (PMID 34497681, 2021). "The results revealed that the tumor volume and weight in the sh-MALAT1 + sh-ABI3BP-treated mice was significantly elevated when compared with the sh-MALAT1-treated mice (p < 0.05)." (PMID 31174563, 2019). "Among the 56 hypomethylated-repressed genes, two candidate tumor-suppressor genes were identified, the hepatic and glial cell adhesion molecule (HEPACAM) and the ABI family, member 3 (NESH) binding protein (ABI3BP)." (PMID 25945129, 2015). "ABI3BP was considerably downregulated in 57 LUAD-paired tissue groups and 49 LUSC tumor groups." (PMID 36744181, 2022). "This indicated that inhibiting the expression of MALAT1 and ABI3BP at the same time could promote the proliferation, invasion and migration of GBC cells, as well as tumor formation." (PMID 31174563, 2019). "In addition, ABI3BP was shown to suppress NSCLC cell migration and invasion, suggesting that its inhibition of these processes may be a crucial factor in reducing tumor progression and metastasis." (PMID 40092729, 2025). "ABI3BP is sensitive to AT7519, indicating that it may play a role in the cell cycle of tumor cells." (PMID 37197424, 2023). "Moreover, while we focused on specific pathways, other signaling networks may also contribute to the tumor-suppressive effects of ABI3BP that have not yet been explored." (PMID 40092729, 2025). "Moreover, ABI3BP is intimately engaged in the regulation of several immunity signaling molecules for lung tumor, including immunity stimulants, immunity suppression, MHC, chemokines, and receptors, therefore influencing the invasion of the immune system in the tumor micro-environment." (PMID 36744181, 2022).
cardiovascular disease (2 papers, 2019 to 2021). "Thus, alteration of ABI3BP expression in the extracellular matrix during cardiovascular disease can be a cause and/or consequence of pathological remodeling." (PMID 30923710, 2019). "Because ABI3BP is present in the cardiovascular system and is altered in cardiovascular disease states, further investigation into ABI3BP's biological and biochemical importance in cardiovascular health and disease is warranted." (PMID 30923710, 2019). "In a recent study, ABI3BP could facilitate the progression of cardiovascular diseases, but this gene might be novel target for GDM." (PMID 33890634, 2021). "This study supports that ABI3BP is a potential contributor to severe cardiovascular disease." (PMID 30923710, 2019). "With further investigation, ABI3BP may prove to be a novel therapeutic target for cardiovascular disease." (PMID 30923710, 2019). "However, reductions in ABI3BP in cardiovascular disease may increase proliferation of key cells involved repair, such as activated fibroblasts (myofibroblasts) and cardiac progenitor cells." (PMID 30923710, 2019). "Thus, ABI3BP may contribute to neuropsychological distress alongside cardiovascular disease." (PMID 30923710, 2019).
kidney diseases (1 paper, 2024). "The role of ABI3BP, an extracellular matrix protein, in kidney disease remains unclear." (PMID 38812032, 2024). "Moreover, using aging-related kidney diseases animal models (GSE145053, GSE126182, GSE79443, GSE189377, and GSE216376), we observed a consistent up-regulation of ABI3BP expression." (PMID 38812032, 2024).
ABI3BP also shares sentences with these, for which no sentence is quoted: colorectal cancer (2 papers); non-small cell lung carcinoma (2); Bladder Urothelial Carcinoma (1); Breast Invasive Carcinoma (1); colon adenocarcinoma (1); cyst (1); endometriosis (1); epilepsy (1); head and neck squamous cell carcinoma (1); heart failure (1); hepatic carcinomas (1); high blood pressure (1); ischemia (1); Kidney Chromophobe (1); lung adenocarcinoma (1); Lung squamous cell carcinoma (1); oligospermia (1); pancreatic adenocarcinoma (1); prostate adenocarcinoma (1); rectum adenocarcinoma (1); Stomach adenocarcinoma (1); teratospermia (1); thyroid (1).